DCAF8 (DDB1 and CUL4 associated factor 8)
Description:
May function as a substrate receptor for CUL4-DDB1 E3 ubiquitin-protein ligase complex.
Synonyms: H326; WDR42A; FLJ35857; GAN2
Tractability: PROTAC: ubiquitination databases record sites on it; its protein half-life has been measured.
Gene: Protein-coding gene on chromosome 1 (160,215,715 to 160,263,388, reverse strand). Ensembl gene ENSG00000132716.
Subcellular location: Nucleus; Cytoplasm
Subcellular location (Human Protein Atlas): Nucleoplasm; Cytosol
Pathways (Reactome):
Metabolism of proteins: Neddylation
Gene Ontology:
Molecular function: protein binding
Biological process: epigenetic regulation of gene expression; protein ubiquitination
Cellular component: Cul4-RING E3 ubiquitin ligase complex; cytoplasm; cytosol; nucleoplasm; nucleus; Cul4A-RING E3 ubiquitin ligase complex; Cul4B-RING E3 ubiquitin ligase complex
Genetic constraint (gnomAD): Loss-of-function variants: 19 observed, 59.78 expected, observed/expected ratio (o/e) 0.32, 90% interval 0.22 to 0.47. The synonymous counts are far from expectation, so gnomAD's model fits this gene poorly and the ratio says little. Missense variants: 436 observed, 763.24 expected, observed/expected ratio (o/e) 0.57, 90% interval 0.53 to 0.62. Synonymous variants: 224 observed, 279.97 expected, observed/expected ratio (o/e) 0.8, 90% interval 0.72 to 0.89.
Homologues: Orthologues: chimpanzee DCAF8 (100% identical), macaque DCAF8 (99% identical), guinea pig DCAF8 (98% identical), rabbit DCAF8 (98% identical), rat Dcaf8 (97% identical), mouse Dcaf8 (96% identical), dog DCAF8 (94% identical), pig DCAF8 (93% identical), tropical clawed frog dcaf8 (84% identical), zebrafish dcaf8 (63% identical), Drosophila melanogaster CG8001 (38% identical). Paralogues in human: DCAF8L2 (71% identical), DCAF8L1 (68% identical), DCAF6 (27% identical), WDTC1 (24% identical), DCAF5 (19% identical).
Diseases named in the same sentence as DCAF8 in open-access papers:
DCAF8 is named in the same sentence as 11 diseases in open-access papers, as found by Europe PMC text mining. Sharing a sentence is not in itself a finding about the gene and the disease. The quoted sentences say what the papers report.
osteosarcoma (2 papers, 2022 to 2023). A usually aggressive malignant bone-forming mesenchymal neoplasm, predominantly affecting adolescents and young adults. "Likewise, DCAF8 lncRNA-associated mRNA, DCAF8, is a ubiquitin-related gene that decreased in osteosarcoma tissues, and together with other ubiquitin-related genes (CORO6, UBE2L3, FBXL5, DNAI1) seem to play a significant role in the clinical outcome of osteosarcoma." (PMID 36831395, 2023). "The expression of ubiquitin-related genes (CORO6, UBE2L3, FBXL5, DNAI1, and DCAF8) showed an obvious significance in normal and osteosarcoma tissues." (PMID 36060009, 2022). "Moreover, the expression of DCAF8 was markedly decreased in osteosarcoma tissues than in adjacent normal tissues, and the expression of UHRF2 and WDR53 was not significant between osteosarcoma and normal tissues." (PMID 36060009, 2022).
breast carcinoma (1 paper, 2023). "DCAF8 interacts with SQSTM1, whose expression has been associated with CSC properties in breast cancer." (PMID 36831395, 2023).
Duchenne muscular dystrophy (1 paper, 2024). Duchenne muscular dystrophy (DMD) is a neuromuscular disease characterized by rapidly progressive muscle weakness and wasting due to degeneration of skeletal, smooth and cardiac muscle. "Among differential gene sets, Duchenne muscular dystrophy gene (DMD) expression and DCAF8 were reduced, which was confirmed by protein analyses." (PMID 38341433, 2024).
esophageal squamous cell carcinoma (1 paper, 2019). Esophageal squamous cell carcinoma (ESCC) is a type of esophageal carcinoma (EC) that can affect any part of the esophagus, but is usually located in the upper or middle third. "However, the degradation degree of circRNA_100367 was much lower than DCAF8 mRNA, indicating circRNA_100367 exists in esophageal squamous cell carcinomas." (PMID 31851619, 2019).
leukemia (1 paper, 2023). A malignant (clonal) hematologic disorder, involving hematopoietic stem cells and characterized by the presence of primitive or atypical myeloid or lymphoid cells in the bone marrow and the blood. "DCAF8 further promotes the degradation of myeloid leukemia factors 1 and 2 (MLF1,2), two factors that are associated with leukemia and several other malignancies, through the ubiquitin-proteasome system." (PMID 36831395, 2023).
lymph node metastasis (1 paper, 2023). "DCAF8 decrease was also marginally associated (p = 0.06) with distal lymph node metastasis, while CHEK1 and PAX8 expressions were significantly correlated with worse overall patients’ survival (p < 0.0001 and p < 0.049, respectively), as evidenced by the relevant Kaplan–Meier curves." (PMID 36831395, 2023).
cancer (2 papers, 2023 to 2024). A tumor composed of atypical neoplastic, often pleomorphic cells that invade other tissues. "DCAF8 is an epigenetic modulator of ferroptosis but also regulates the function of myeloid leukemia factor, which has been linked to various forms of cancers." (PMID 39337373, 2024). "The expression of DCAF8 and PAX8 in tumors illustrates patterns of significant downregulation (p = 0.0262) and upregulation (p = 0.00174) across cancer stages 1 and 3, respectively." (PMID 36831395, 2023).
tumor (1 paper, 2023). "Furthermore, in silico analysis revealed that among the four identified lncRNAs, DCAF8 expression is inversely correlated with tumor stage and nodal metastasis, thus suggesting its potential suppressing role in PDAC aggressiveness, likely through regulation of CSC features." (PMID 36831395, 2023). "Likewise, ATF2, CHEK1, DCAF8, and PAX8 showed diverse expression across the different tumor grades." (PMID 36831395, 2023).
DCAF8 also shares sentences with these, for which no sentence is quoted: Ataxia (1 paper); ischemic stroke (1); neuropathy (1).